METTL3 (methyltransferase 3, N6-adenosine-methyltransferase complex catalytic subunit)
Diseases named in the same sentence as METTL3 in open-access papers (continued):
Sharing a sentence is not in itself a finding about the gene and the disease.
tumor (continued). "In addition, knockdown of METTL3 promoted tumor proliferation and metastasis." (PMID 31921660, 2019). "In addition, METTL3-mediated m6A modification can directly regulate the transcription and translation of oncogenes and tumor suppressors coupled to the most of the important pathways involved in cancer cell progression, such as the PI3K/AKT, wnt/β-catenin, and P38/ERK pathways." (PMID 31921660, 2019). "Additionally, up-regulation of METTL3 significantly suppressed tumor growth in vivo." (PMID 29221190, 2017). "We observed that METTL3, WTAP and FTO transcript and protein expression were significantly increased in cells derived from invasive regions of GBM tumours, and elevated WTAP and FTO expression significantly correlated with poor GBM patient survival." (PMID 41752103, 2026). "As a result, circLPAR1 can hinder the interaction between Mettl3 and EIF3H, leading to a reduction in the translation of the oncogene bromodomain-containing protein 4 and subsequently inhibiting tumor growth." (PMID 41517663, 2026). "The interplay between glutamate signaling, calcium influx, CaMKII/ERK-MAPK pathway activation, Mettl3 expression, HK2 upregulation, enhanced glycolysis, and PNI highlights the complex molecular mechanisms involved in PDAC progression and tumor behavior." (PMID 41517663, 2026). "Collectively, these outcomes support a tumor-suppressive role for METTL3 in ICCA and underscore the broader impact of METTL3-mediated m6A methylation on ICCA growth." (PMID 41208889, 2025). "In various cancer tissues, the METTL3 and METTL14 complexes play diverse roles, functioning as both oncogenes and tumor suppressors." (PMID 39802639, 2025). "The study found that m6A and its writer protein METTL3, eraser protein FTO, and reader protein YTHDF2 play an essential role in CAFs promoting tumor cell metastasis and angiogenesis." (PMID 40356596, 2025). "Elevated levels of METTL3 have been found in both the cytoplasm and nucleus of OS cells, which promote ATAD2 expression that consequently facilitates tumour cell proliferation, migration, and invasion while suppressing apoptosis." (PMID 40052548, 2025). "This binding disrupts WTAP-methyltransferase-like protein 3 (METTL3)–methyltransferase-like protein 14 (METTL14) complex formation, reducing overall m6A modification in tumor cells, inhibiting HCC cell growth." (PMID 41181701, 2025). "Recent investigations have revealed aberrant expression and dysregulation of METTL3 in CRC, indicating its potential involvement in tumor progression." (PMID 40177651, 2025). "CEBPA participates in chemoresistance through METTL3/METTL14/BHLHB9 in vivo, which accelerated the tumor growth." (PMID 40297811, 2025). "In the hypoxic TME, HBXIP-activated METTL3 binds to HIF-1α, facilitating its m6A modification to enhance hypoxia-adaptive metabolic reprogramming and aggressive tumor behaviors." (PMID 40986143, 2025). "METTL3/14, YTHDF2/YTHDC1 proteins work to maintain the activity of oncogenes, inhibit tumor suppressor genes, and drive cancer development by regulating m6A RNA modification." (PMID 41446042, 2025). "METTL3 KD increases the expression of SLC7A11, further suppressing the erastin sensitivity of tumor cells in vivo." (PMID 39800682, 2025). "While most previous studies recognize that METTL3 and METTL14 are important to cancer cell survival, one study showed that METTL3 enhanced the tumor suppression activity of p5346." (PMID 38853928, 2025). "The m6A‐YTHDF1 axis increases JAK1 protein translation efficiency and subsequent STAT3 phosphorylation, thus forming the METTL3/m6A/JAK1/STAT3 axis, which enhances TIMs’ immune suppressive functions and facilitates tumor immune evasion." (PMID 40443721, 2025). "In BLCA cells, downregulation of METTL3 reduced m6A modification in PD-L1 mRNA, thereby decreasing its stabilization by IGF2BP1, which enhanced the cytotoxicity of CD8 + T cells against tumor cells." (PMID 39987091, 2025).
tumor (continued). "The combination therapy greatly suppressed tumor growth in TRIM21 overexpression tumors, but the therapeutic efficacy of immunotherapy was significantly impaired in METTL3 high expression tumors." (PMID 40175350, 2025). "Mechanistically, LPS enhances tumor aggressiveness via METTL3-mediated PI3K/AKT pathway activation, promoting tumor cell migration and invasion." (PMID 41018102, 2025). "We investigated METTL3’s interaction partners to learn more about its function in COADREAD and how it promotes tumor detection, carcinogenesis, and growth." (PMID 40177651, 2025). "Consistently, m6A levels in Smad3 mRNA were significantly reduced following Mettl3 knockdown in tumor MO-MDSC, accompanied by a notable elevation in Smad3 transcription levels, while Mettl3 overexpression decreased Smad3 expression." (PMID 41360769, 2025). "In vivo experiments in mice confirmed that METTL3 increased BFSP1 stability by promoting m6A modification of BFSP1 mRNA, and knockdown of BFSP1 inhibited tumor growth and metastasis." (PMID 40097750, 2025). "Generally speaking, METTL3 promotes glycolysis via increasing the m6A modification of SRPK1, thereby facilitating tumor progression." (PMID 40823087, 2025). "Inhibitors targeting METTL3, such as STM2457, suppress tumor cell metabolism by blocking m6A modification, significantly reducing invasive and metastatic potential." (PMID 41163091, 2025). "The METTL3/METTL14 complex can activate the AKT pathway by promoting the expression of ADAMTS9 and miR-380-3p to promote tumor angiogenesis and EMT." (PMID 41194259, 2025). "METTL3, for instance, positively regulates the expression of lncRNA MALAT1 in PC cells, which enhances PD-L1 expression and modulates tumor immune surveillance." (PMID 39897038, 2025). "In tumor-infiltrating myeloid cells (TIMs), lactate accumulated in TME not only increases the expression of methyltransferase-like 3 (METTL3) in TIMs through lactonization, but also induces immunosuppression in TIMs." (PMID 40421024, 2025). "Given the aberrant m6A levels and METTL3 and METTL14 expression levels, we proceeded to investigate their potential roles in the tumour biological behaviour of GBC." (PMID 40785027, 2025). "The results showed that METTL3 overexpression promoted the expression of BFSP1, METTL3, and TMOD4 in mouse tumor tissues, whereas sh-BFSP1 reversed the effect." (PMID 40097750, 2025). "In parallel, propionate alters histone acetylation and affects methyltransferase-like 3 (METTL3)–mediated m6A deposition, promoting tumor survival and therapy resistance through the regulation of lipid metabolism and ferroptosis tolerance." (PMID 41357193, 2025). "METTL3 functions as a pro-oncogene in AML, and targeting METTL3 has the potential to impede tumor progression." (PMID 40169588, 2025). "In HCC, TGF-β-induced METTL3-mediated m6A modification destabilizes ITIH1 mRNA, disrupting fibronectin and focal adhesion kinase signaling, thus driving tumor growth and invasion." (PMID 40034695, 2025). "Multivariate Cox regression analyses were conducted to assess the independent prognostic value of METTL3, METTL14 and CBLL1 expression whilst accounting for the potential confounding variables of nodal stage, tumour size, patient age, ER status and LVI." (PMID 41310336, 2025). "For instance, studies have highlighted the significance of RNA methylation regulators like METTL3 and ALKBH5 in shaping tumor behavior by modulating m6A RNA modifications, providing promising avenues for BLCA treatment." (PMID 39991573, 2025). "While regulators like METTL3 and FTO largely drive oncogenesis, others, most notably METTL14, exert potent tumor-suppressive effects, underscoring the critical importance of context-specific understanding." (PMID 41312360, 2025). "In clear-cell renal cell carcinoma (ccRCC), multiple m6A enzymes- including the writer METTL3 and demethylase ALKBH-are significantly overexpressed in tumor tissue vs normal kidney." (PMID 40895041, 2025).
tumor (continued). "Taken together, these studies reveal that the interplay between METTL3, METTL14 and WTAP fine-tunes m6A methylation activity, influencing the balance between CSC maintenance and differentiation across tumor types." (PMID 41228380, 2025). "In parallel, the tumor suppressor BRD7 radiosensitizes NPC by disrupting USP5-METTL3 binding, which reduces METTL3 stability and inhibits BRCA1/RAD51-mediated DNA damage repair." (PMID 40823093, 2025). "Most regulators, such as METTL3, YTHDF1, IGF2BP3, and RBMX, were upregulated in tumor tissues, while METTL14 and ZC3H13 were downregulated." (PMID 40916616, 2025). "Collectively, these findings suggest that the targeted inhibition of METTL3 and FTO, in combination with radiotherapy, enhances the suppression of tumor growth and progression." (PMID 40823093, 2025). "For example, RNA methyltransferase METTL3-mediated m6A modification enhances the translation of the oncogenes EGFR and TAZ, thereby promoting tumor cell proliferation, survival, and invasion." (PMID 40859309, 2025). "Research indicates a relationship between the downregulation of NEAT1 and METTL3, resulting in diminished methylation of NEAT1 in ccRCC cells, which in turn facilitates tumor cell proliferation and migration." (PMID 40313614, 2025). "To investigate the relationship between METTL3 or IGF2BP2 and radiosensitivity in vivo, we established a mouse xenograft model and irradiated the primary tumor site using irradiator." (PMID 39799112, 2025). "Current research on methyltransferases, particularly METTL3, METTL14, and WTAP, primarily focuses on their roles in regulating ferroptosis and tumor growth." (PMID 40271153, 2025). "The results revealed a significant positive correlation between the expression of METTL3 and IGF2BP3 and EMP1 in tumor cells." (PMID 41285728, 2025). "The results demonstrate that the targeted inhibition of METTL3 by STM2457, when combined with in vivo radiotherapy, synergistically suppresses tumor growth." (PMID 40823093, 2025). "Mechanistically, METTL3 overexpression in advanced RCC is driven by HIF-1α in hypoxia, facilitating m6A-dependent PLOD2 upregulation to drive tumor proliferation and metastasis." (PMID 40895041, 2025). "METTL3 is responsible for mediating the m6A modification of circMYO1C to enhance its stability by recognizing IGF2BP2 and playing a role in tumor progression." (PMID 39904996, 2025). "METTL3 and METTL14 participate in most m6 A modifications of mRNA and act as tumor suppressors or oncoproteins in various cancers." (PMID 40483535, 2025). "The writer enzyme METTL3 facilitates tumor growth by stabilizing oncogene mRNA, whereas erasers such as FTO and ALKBH5 suppress tumor progression by removing m6A marks." (PMID 40034695, 2025). "In nude mouse models, administration of the GLI1 inhibitor GANT58 and the METTL3 inhibitor SAH, individually or in combination, markedly delayed tumor growth, with the combined treatment showing superior efficacy." (PMID 40740874, 2025). "Regarding protein expression, varying intensities of METTL3, METTL14 and CBLL1 staining was observed in the nuclei of tumour epithelial cells by IHC." (PMID 41310336, 2025). "Western blotting revealed significant upregulation of PUM2, METTL3, and IGF2BP2 in tumour tissues compared with normal controls." (PMID 40629911, 2025). "To further validate the role of METTL3 in TSC tumorigenesis in vivo, we performed a xenograft tumor formation assay using nude mice." (PMID 41238564, 2025). "Knockdown of METTL3 or inhibition of methylation using 3-DAA and UZH1a resulted in decreased viability of EBV-positive tumor cells." (PMID 40778336, 2025). "The inhibition of METTL3, combined with anti-PD1 therapy, has shown promising anti-tumor effects in CRC." (PMID 40825934, 2025).
tumor (continued). "METTL3 induces the degradation of decapping protein 2 (DCP2), resulting in reduced inhibition of PINK1 and Parkin with enhanced mitophagy, alleviated tumor cell dysfunction levels and increased chemotherapy resistance in small cell lung cancer (SCLC)." (PMID 41373022, 2025). "Mechanistically, the inhibition of METTL3 reduces the m6A level of asparagine synthetase (ASNS) mRNA, thereby downregulating ASNS expression and exerting anti-tumor effects." (PMID 40823087, 2025). "The key m6A-related genes METTL3 and METTL14 were reported to be active components of the m6A methyltransferase complex and correlated with tumor proliferation, differentiation, tumorigenesis, invasion, and metastasis." (PMID 40123906, 2025). "At the genetic level, studies have shown that silencing Caprin-1 can significantly inhibit the proliferation and glycolytic activity of EC cells while reducing the expression of METTL3 and WTAP, thereby suppressing tumor growth." (PMID 41458606, 2025). "Our research study found that METTL3 mediated the m6A modification of ZNF384 in NSCLC, which in turn enhanced the expression of ZNF384 and influenced its regulatory role in tumor metastasis." (PMID 40717692, 2025). "Deleting METTL3 specifically in NK cells reduced their numbers and effector functions, impaired IL-15 responsiveness (via AKT–mTOR/MAPK signaling), and accelerated tumor progression in mice." (PMID 41280938, 2025). "Further mechanistic analysis revealed that METTL3 increases AXL mRNA expression, a process that accelerates the EMT, which in turn promotes the proliferation, tumour formation, migration, and invasion of OC cells." (PMID 40356909, 2025). "Overall, the roles of METTL3 and METTL14 in regulating GPX4 and SLC7A11 are central to current research on m6A methyltransferase-mediated ferroptosis and its impact on tumor growth." (PMID 40271153, 2025). "The stapled peptide inhibitor RSM3 disturbs METTL3-METTL14 complex formation and induces its proteasomal degradation, significantly inhibiting tumor growth and RNA methylation in tumor models." (PMID 40651967, 2025). "Parallelly, STC-15, another METTL3 inhibitor analogous to STM3006, contributes to the innate immune response and reduces tumor growth via T cell checkpoint blockade treatments, such as anti-PD-1 therapy." (PMID 40002173, 2025). "METTL3 activates the Wnt/β-catenin signaling pathway by regulating the SALL4 target, promoting the renewal of tumor stem cells, leading to radiotherapy resistance in OSCC." (PMID 40823093, 2025). "Once it was reported that in oral squamous carcinoma (OSCC) METTL3 enhanced the stability of SLC7A11 and regulated the proliferation, invasive and migrative ability of tumor cells, and thus promoted the progression of OSCC." (PMID 39799112, 2025). "Recent studies have shown that METTL3 plays a key role in the TME, and its increased expression in OC tissues is significantly correlated with the clinical characteristics of tumours." (PMID 40356909, 2025). "Functional studies have demonstrated that silencing METTL3 markedly reduces cell proliferation, migration, and invasion of OSCC cells in vitro and reduces tumor volume, tumor weight, proliferation, and lymphatic metastasis in vivo." (PMID 40338154, 2025). "The METTL3-YTHDC2 axis stabilizes LINC00894 mRNA in an m6A-dependent manner and subsequently inhibits tumour malignancy through the Hippo signalling pathway." (PMID 38291427, 2024). "In this pathway, JNK interacts with and binds to METTL3, which increases the m6A modification of mRNA, thereby elevating PD-1 levels and reducing the cytotoxic effectiveness of CD8+ T cells, leading to tumor immune evasion." (PMID 38902779, 2024). "By inducing Mettl3-mediated m6A modification in T cells, the expression of integrin α subunit ITGB1 can be upregulated, thereby enhancing T cell tumor infiltration and antitumor activity, and relieving the suppression of T cells by the acidic microenvironment." (PMID 39372415, 2024).
tumor (continued). "Specifically, the m6A writers METTL3, WTAP, and RBM15B and the m6A readers YTHDF1 and HNRNAPA2B1 showed significant upregulation in the high PCa tumor grades compared to the low tumor grades and adjacent normal tissues." (PMID 38610981, 2024). "While METTL3 is highly expressed in tumours of all CC patients, human papillomavirus (HPV)-positive patients exhibit even higher METTL3 expression compared to HPV-negative patients (Ref." (PMID 39377535, 2024). "It was reported that METTL3 regulates HDGF in an m6A-mediated manner to promote tumor angiogenesis and glycolysis and also regulates ZMYM1, SPHK2, and MYC to promote GC tumor metastasis." (PMID 39195675, 2024). "m6A methylation enhances PD-1/PD-L1 expression and reduces the cytotoxicity of CD8+ T cells through the METTL3-JNK signaling pathway, leading to tumor immune escape." (PMID 39726589, 2024). "In summary, our in vitro and in vivo experiments have elucidated the differing roles of METTL3 and METTL14 proteins in tumor cell proliferation capability." (PMID 38965238, 2024). "Recently researches have indicated that molecules involved in m6A methylation modification, such as METTL3 and YTHDF2, play an important role in promoting the anti-tumor activity of NK cells." (PMID 39439794, 2024). "In conjunction with YTH N6-methyladenosine RNA Binding Protein 1 (YTHDF1), METTL3 mediates m6A modification on JAK1 mRNA, enhancing JAK1 and STAT3 expression and promoting tumor immune escape." (PMID 39659524, 2024). "In NSCLC, the suppression of METTL3 can enhance the sensitivity of tumor-bearing mice to anti-PD-1 treatment, and patients with NSCLC exhibiting low METTL3 expression have a more favorable prognosis with immunotherapy." (PMID 39372415, 2024). "For exerting its function, METTL3 enhanced HDGF mRNA stability, then HDGF activates GLUT4 and ENO2 expression to increase glycolysis, accompanied by tumor growth and metastasis to liver." (PMID 38075202, 2024). "LINC02253 stabilizes KRT18 mRNA and upregulates KRT18 expression by promoting the recruitment of METTL3 to KRT18 mRNA, activating the MAPK/ERK signaling pathway, and promoting tumor growth and GC cell migration and invasion." (PMID 39678510, 2024). "Changes in the activity of key methylases such as METTL3 and ALKBH5 can significantly affect the response of tumor cells to chemotherapy and radiotherapy." (PMID 39473440, 2024). "IGF2BP1, HNRNPA2B1, FTO, WTAP promote the EC progression, but METTL3, METTL14, YTHDF2 work as tumor suppressors in EC." (PMID 39582531, 2024). "This review aims to systematically summarize the functions of METTL3 in TME, particularly its effects on tumor-infiltrating immune cells." (PMID 38322265, 2024). "METTL3 cooperates with YTHDF2 through the c-Rel and NF-κB pathways to change Tan invasion and repress tumor growth, thereby inhibiting the occurrence and development of PTC." (PMID 39403369, 2024). "Since then, several cancer studies related to METTL3 have also used STM2457 and validated its efficacy in inhibiting tumor progression 20,21." (PMID 39132158, 2024). "Currently, METTL3/14 and FTO have emerged as the most extensively reported m6A regulators during tumor development, with a majority of small molecule interventions targeting these two targets." (PMID 38711100, 2024). "The IHC and western blot results showed that both GL‐1 and GC‐7, as DHPS inhibitors, inhibited METTL3, YTHDF2, and YTHDC1 in tumor tissues." (PMID 38952061, 2024). "For instance, in an orthotopic liver tumor model, the ablation of the METTL3/FOXO3 axis was reported to weaken the antitumor efficacy of sorafenib, leading to enhanced tumor autophagy, angiogenesis, and a subsequent acceleration of tumor growth." (PMID 38566136, 2024). "Research shows that the m6A writer METTL3 is a key regulator in cancers such as liver, gastric, and ovarian cancers, as it promotes EMT and tumor progression." (PMID 39695216, 2024).